INSR (insulin receptor)
Diseases named in the same sentence as INSR in open-access papers (continued):
Sharing a sentence is not in itself a finding about the gene and the disease.
Insulin resistance (continued). "ApoE2/2 mice without insulin resistance, which had a single allele of the insulin receptor deleted, will not enhance the severity of atherosclerosis." (PMID 29164077, 2017). "Phospho-Ser307 in IRS-1 blocks the interaction between the IRS-1 PTB domain and insulin receptor, which might weaken the coupling between the two proteins and lead to insulin resistance." (PMID 28634451, 2017). "Further analysis of the data and discussion of the implication of miR-96 in insulin resistance and the pathogenesis of type 2 diabetes are presented in "Induction of miR-96 by dietary saturated fatty acids exacerbates hepatic insulin resistance through the suppression of INSR and IRS-1"." (PMID 29124099, 2017). "Our data indicate that post-receptor signalling abnormalities might contribute to DM insulin resistance regardless the alteration of INSR splicing." (PMID 28915272, 2017). "However, if prolonged, the elevated TNF-α level can be deleterious, even leading to insulin resistance by downregulating the tyrosine kinase activity of the insulin receptor." (PMID 29163201, 2017). "We next confirmed the prediction that vitamin D can prevent quetiapine-induced insulin resistance in a mouse model by examining the ability of cholecalciferol diet to block drug-provoked changes in gene expression related to the insulin receptor signalling pathway." (PMID 27199286, 2016). "Therefore, the upregulation of miR-96 provokes an impairment of insulin signaling and glycogen synthesis in hepatocytes through the repression of INSR and IRS-1, and that miR-96 is a causal factor for SFA-induced hepatic insulin resistance." (PMID 28036389, 2016). "Increased expression of the E3 ubiquitin ligases Atrogin‐1/FBX032 and TRIM63/MuRF‐1 were measured following injury, as was skeletal muscle insulin resistance, as evidenced by decreased insulin‐inducible insulin receptor (IR) and AKT/PKB (Protein Kinase B) phosphorylation." (PMID 26818585, 2016). "In the NAFLD liver, modulation of miR-15b may be correlated with the pathogenesis of hepatic insulin resistance, as it directly targets the insulin receptor (INSR)." (PMID 26950158, 2016). "Therefore, the age-related decline in mitochondrial function seems to disrupt insulin receptor activation in neurons and lead to the development of cerebral insulin resistance in old age." (PMID 27531979, 2016). "To test brain insulin resistance, we measured cortical levels of glucose and insulin and analyzed the expression and activation of the insulin receptor (IR) and its downstream signaling molecules IR scaffold-1 (IRS1), protein kinase B (AKT) and mammalian target of rapamycin (mTOR)." (PMID 26858121, 2016). "However, liver‐specific insulin receptor knock out (LIRKO) mice develop severe insulin resistance, but lack the hepatic steatosis, suggesting divergent signalling pathways in the stimulation of lipogenesis and inhibition of gluconeogenesis." (PMID 25740151, 2016). "Although IRS-1 serine phosphorylation by SFA is considered as an emerging detrimental factor in insulin sensitivity, a growing lines of evidence have suggested that the reduction of INSR expression also promotes the pathogenesis of insulin resistance and diabetes." (PMID 28036389, 2016). "Use of more clinically relevant models of insulin resistance (such as defects in insulin receptor or post-receptor signaling components) should help to better understand the role of PGC-1α and its post-translational modification in the progression of insulin resistance-induced cardiomyopathy." (PMID 27634872, 2016). "Furthermore, anti-insulin immunoglobulin G (IgG) antibodies and anti-insulin receptor antibodies are occasionally detected in patients with diabetes who have brittle glycemic control or severe insulin resistance." (PMID 27456688, 2016).
Insulin resistance (continued). "To organize discussion of this topic, we differentiate between primary mechanisms of insulin resistance – due to impaired insulin-to-insulin-receptor signaling – and secondary mechanisms of insulin resistance, such as impaired glucose uptake or inappropriately elevated glucose production." (PMID 27053133, 2016). "We examined whether HUA induces insulin resistance are insulin receptor-mediated or can be ascribed to activation of the IGF1R in H9c2 cells." (PMID 26836389, 2016). "One possible explanation for the discordance between INSR- and AKT2-associated human insulin resistance subphenotypes lies in the pronounced femorogluteal lipodystrophy associated with AKT2 mutation, albeit only in a single family to date, but not with INSR mutations." (PMID 27766312, 2016). "To explore which organ may be responsible for insulin resistance, we analyzed insulin-induced phosphorylation of the insulin receptor (p-IRβ)." (PMID 25757720, 2015). "Furthermore, TBK1 is involved in the inflammatory response in obesity and hypertension and contributes to phosphorylation of the insulin receptor thus impairing its function and supporting insulin resistance." (PMID 25997745, 2015). "Alternatively, insulin resistance in podocytes may occur independently of other tissues and/or the INSR/PI3K/XBP1 pathway may be selectively impaired in podocytes, reflecting cell or pathway selective insulin resistance." (PMID 25754093, 2015). "Changes in INSR isoform ratio that favour INSRA in metabolically active tissues such as the liver may have important implications in the pathogenesis of insulin resistance." (PMID 25742416, 2015). "Finally, an immunoprecipitation assay was strongly positive for anti-insulin-receptor antibodies, confirming the diagnosis of type B insulin resistance." (PMID 25675382, 2015). "Therefore, it is unclear how the PKCε-mediated impingement on insulin receptor activity fits with this widely observed concept and meshes into the broader model of hepatic insulin resistance." (PMID 26273583, 2015). "Using the liver insulin receptor knockout (LIRKO) mouse as a model of pure hepatic insulin resistance it has been demonstrated that hepatic insulin resistance alone can produce both the dyslipidemia and increasing risk of atherosclerosis associated with the metabolic syndrome." (PMID 26089893, 2015). "HFD, while causing overt diabetes and marked insulin resistance, does not independently affect coronary tone and the balance of cardiac molecular pathways downstream insulin receptor." (PMID 25093405, 2014). "To test this hypothesis, we induced transient insulin resistance in healthy, lean wild-type mice with the insulin-receptor antagonist S961." (PMID 25233132, 2014). "Insulin resistance may occur secondary to resistance at the insulin receptor, decreased hepatic clearance of insulin, and/or increased pancreatic sensitivity." (PMID 25114673, 2014). "Several molecules inhibit insulin signaling through the insulin receptor (INSR) and may contribute to pathogenesis of insulin resistance." (PMID 25539584, 2014). "However, hyperinsulinemia is believed to be a compensatory response to insulin resistance, which is related to a defect in signaling downstream of the insulin-receptor in many organs, including the heart." (PMID 24416343, 2014). "First, it can directly phosphorylate insulin receptor substrate protein-1 (IRS-1) on serine residues, leading to attenuation of tyrosine kinase-mediated signaling from the insulin receptor, interference of normal insulin action, and subsequent insulin resistance." (PMID 23577240, 2013). "Impaired proximal signaling of insulin receptor also mediates insulin resistance." (PMID 23781214, 2013). "Hyperinsulinemia can promote insulin resistance through downregulation of the insulin receptor." (PMID 24252636, 2013).
Insulin resistance (continued). "In 5αR1−/− but not 5αR2−/− mice, mRNA expression changes were consistent with the development of insulin resistance, with decreased insulin receptor expression, and this may have contributed to the observed hepatic phenotype." (PMID 24080367, 2013). "There was a negative correlation between insulin resistance levels and pTyr1R suggesting that the increased insulin resistance in the body may disrupt insulin receptor signaling in the brain." (PMID 23896654, 2013). "In addition to stress kinase activation and reduced insulin receptor expression, insulin resistance can also be induced by over activation of tyrosine phosphatases." (PMID 24252636, 2013). "Indeed, liver-specific knockout of the insulin receptor has demonstrated the critical role of hepatic insulin resistance in metabolic abnormalities." (PMID 23560040, 2013). "Type B syndrome is insulin resistance mediated by anti-insulin receptor antibodies." (PMID 23424687, 2013). "In addition, metformin increases the affinity of insulin for the insulin receptor, which reduces insulin resistance." (PMID 23983688, 2013). "Moreover, adiponectin has been shown to ameliorate insulin resistance through insulin receptor substrates (IRSs) in the liver." (PMID 24223187, 2013). "Another possible component of the insulin receptor signaling pathway that could be affected in insulin resistance is PTP1B." (PMID 24252636, 2013). "Although most taste bud cells express insulin receptor, obesity-associated insulin resistance does not play a role in the preference for oily solution." (PMID 23840049, 2013). "In addition, mutations of DM1 kinase gene causes defective alternative splicing of INSR, and mutations of high-mobility group A1 (HMGA1) gene suppress the expression of INSR resulting in insulin resistance." (PMID 23781214, 2013). "Nevertheless, the relationship between obesity and insulin resistance is a result of changes in the insulin signal transduction pathway, with a decrease in kinase activity of insulin receptor (IR), insulin receptor substrate 1 and 2 (IRS1, IRS2), and phosphatidylinositol 3-kinase (PI3K), or both." (PMID 23046739, 2012). "Since mitochondrial H2O2 is required for insulin receptor activation, it is obvious that some alterations in mitochondrial function could result in a malfunction in insulin receptor activation and insulin resistance." (PMID 23730255, 2012). "This may counteract the diminished phosphorylation of the insulin receptor in the liver, avoiding insulin resistance." (PMID 22470480, 2012). "In vitro models using liver cells have also found DEHP to reduce insulin receptor concentrations and glucose oxidation, suggesting that phthalates may lead to insulin resistance." (PMID 22796563, 2012). "Given the fact that these mice are normoglycemic despite insulin resistance, we speculate that they have higher insulin levels due to compensatory secretion of insulin from pancreas, similar to liver insulin receptor knockout (LIRKO) mice." (PMID 23115649, 2012). "Therefore, the age-related decline in mitochondrial functions seems to disrupt insulin receptor activation in neurons and lead to the development of cerebral insulin resistance in old age." (PMID 23730255, 2012). "Excessive FA delivery into hepatocytes results in accumulation of intermediate lipid metabolites such as diacylglycerol, which can activate protein kinase C (PKC) that, in turn, binds to the insulin receptor and inhibits its tyrosine kinase activity leading to hepatic insulin resistance." (PMID 22238690, 2012). "In view of the ultrasensitivity of insulin receptor autophosphorylation to antioxidant activity in neurons, the elevated activity of the antioxidant systems in AD may contribute to dysfunctional insulin receptor activation and central insulin resistance." (PMID 23730255, 2012). "Hallmarks of T2DM are the presence of insulin resistance and insulin receptor insensitivities." (PMID 22107728, 2011).
Insulin resistance (continued). "This approach becomes even more appealing in light of new data demonstrating, that in isolated, genetically induced endothelial insulin resistance (mediated by endothelial-specific insulin receptor knock-out), dramatically enhanced development of atherosclerosis in an ApoE-deficient mice model." (PMID 21635764, 2011). "ER stress down-regulates insulin receptor signaling and triggers insulin resistance." (PMID 19558691, 2009). "Given the critical role of insulin resistance in these patients it was informative in that molecules immediately down stream of the insulin receptor appeared to be down regulated, such as IRS1, CD36 and JAK1/2 (a tyrosine kinase associated with cytokine and metabolic signalling)." (PMID 18997871, 2008). "Since this proteolytic system is involved in the control of receptor-associated (tyrosine-kinase activity insulin receptor), it is postulated here that the mechanism of TNF-α-induced insulin-resistance is mediated by the activation of the UPS-dependent proteolysis." (PMID 17971205, 2007). "Therefore, our results suggest that the sustained hyperinsulinemia produced by E2 and BPA affects peripheral tissues, producing insulin resistance, most likely by down-regulation of insulin receptor number and function." (PMID 16393666, 2006). "Constitutive knock‐in mice with the P1195L mutation in the insulin receptor (IR‐KI mice) and those with a mutated amyloid precursor protein (AppNL‐G‐F mice: APP‐KI mice) were crossbred to obtain the resultant mice (APP/IR‐dKI mice) as AD models with insulin resistance for behavioral analysis." (PMID 40443027, 2025). "Notably, BACE1 could cleave the insulin receptor (InsR), leading to reduced InsR levels, which may impair insulin signaling and contribute to insulin resistance." (PMID 40507910, 2025). "This could be attributed to either higher expression of cathepsin enzymes or the increased acidic nature of the lysosomes, which favors more rapid dissociation of insulin from the insulin receptor in LL:AA myotubes, thereby terminating insulin signaling and contributing to insulin resistance." (PMID 41004571, 2025). "Moreover, the molecular pathways of chronic inflammation, which lead to insulin resistance, a decrease in insulin receptor levels, and apoptosis induction in pancreatic cells, must also be targeted to develop innovative therapeutic approaches for T2DM treatment." (PMID 39062550, 2024). "These mice displayed absent phosphorylation of both the insulin receptor and Akt, suggesting that long-chain ceramides may have a role in facilitating intracellular insulin receptor translocation, thereby protecting against the development of insulin resistance." (PMID 39408263, 2024). "What if one of the major causes of insulin resistance is not related to defects in the target tissues and/or insulin receptor signaling, but rather to a reduced survival of endogenously secreted insulin on its way to activating the receptor on the cell surface of the target tissues?" (PMID 40604313, 2024). "Indeed, in humans, the downregulation of INSR in adipose tissue is an early molecular event which has been recognized to contribute to the development of adipocyte dysfunction and, eventually, systemic insulin resistance." (PMID 38891115, 2024). "There is evidence that liver cells exposed to high levels of glucose, fructose, or sucrose induce insulin resistance in rodents, Consequently, insulin receptor signaling could be suppressed by decreased insulin receptor expression or increased phosphorylation of insulin receptor substrate 1 (IRS-1)." (PMID 38323033, 2024). "While changes in INSR or downstream pathways are most often evoked to explain insulin resistance at the molecular level, it must also be kept in mind that the bioactivity of insulin itself may vary according to its quaternary structure or soluble component in the surrounding matrix." (PMID 37611907, 2024).
Insulin resistance (continued). "High levels of IFN-γ produced by NK cells in response to persistent infection cause insulin resistance in skeletal muscle by downregulating insulin receptor transcription in myocytes but without this occurring in the liver, as it does in type 2 diabetes mellitus." (PMID 37718435, 2023). "In addition, the interaction between MAFLD and insulin resistance increases the levels of very low-density lipoprotein particles and triglycerides, leading to insulin receptor dysfunction, which mobilizes liver adipose tissue for transport to peripheral tissue and increases the risk of HF." (PMID 37355613, 2023). "In regard to insulin resistance, some studies suggest that heightened amino acid levels in the blood intervene with insulin uptake via overactivation of the mTORC1 pathway, which increases phosphorylation of insulin receptor substrates and induces pancreatic beta cell dysfunction/degradation." (PMID 38068805, 2023). "Thus, targeting intracellular signaling components to restore striatal InsR signaling in conditions that promote insulin resistance could be therapeutically beneficial." (PMID 36979453, 2023). "Here we established an AD model with whole‐body insulin resistance without persistent hyperglycemia (APP/IR‐dKI mice) by crossbreeding constitutive knock‐in mice with P1195L‐mutated insulin receptor (IR‐KI mice) and those with mutated amyloid precursor protein (AppNL‐G‐F mice: APP‐KI mice)." (PMID 37822109, 2023). "Surprisingly, we found that cellular senescence did not cause insulin resistance in hepatocytes, but rather increased insulin sensitivity, as measured by the robust increase in insulin receptor signaling following acute insulin stimulation (pIR, pAkt, pMAPK and PTP1B)." (PMID 36072934, 2022). "It has been reported that TNF-α is the key mediator of insulin resistance because it can reduce insulin signaling by potently inhibiting insulin receptor (IR) tyrosine kinase, which might reduce the ability of IRS-1 to transduce signals in the insulin signaling system." (PMID 35320949, 2022). "Additionally, they have lower hepatic insulin clearance and increased insulin production, which probably could lead to increased insulin resistance, since chronic hyperinsulinemia can lead to insulin receptor desensitization." (PMID 36313112, 2022). "Besides, long-term use of insulin may decrease insulin receptor sensitivity, resulting in insulin resistance." (PMID 35056765, 2022). "Consequently, excess fatty acid influx into skeletal muscle and liver promotes diacylglycerol-induced insulin resistance, which impairs insulin signaling via increased insulin receptor serine phosphorylation, and worsens with disrupted mitochondrial oxidative phosphorylation." (PMID 35012577, 2022). "Therefore, hyperinsulinemia‐induced insulin resistance may be mediated by a reduction in total INSR that results in a proportional reduction in INSR protein at the cell surface." (PMID 34921686, 2022). "Moreover, a subcellular distribution of insulin receptor might be a contributing factor to insulin resistance." (PMID 36230978, 2022). "The change in TGs is somewhat reminiscent of the well-described absence of dyslipidemia in patients with monogenic severe insulin resistance due to biallelic or monoallelic INSR mutations, so again this does not preclude the INSR LOF variants being associated with reduced insulin sensitivity." (PMID 34875679, 2022). "Non-obese patients with extreme insulin resistance due to pathogenic variants in the insulin receptor (Rabson-Mendenhall syndrome) and high circulating insulin levels have been found to have thyromegaly, supporting insulin as a mediator of the link between common obesity and thyroid proliferation." (PMID 35158824, 2022). "Our data indicate that insulin receptor levels in gastrocnemius muscle alone might not directly cause insulin resistance; somewhat altered phosphorylation or affected downstream signaling may account for a decreased insulin sensitivity in OZRs." (PMID 36547071, 2022).